AQP3 (aquaporin 3 (Gill blood group))
Diseases named in the same sentence as AQP3 in open-access papers (continued):
Sharing a sentence is not in itself a finding about the gene and the disease.
breast carcinoma (continued). "Once recognized as overexpressed in cancer, AQP3 was getting in the focus as a possible prognostic marker for triple negative breast cancer together with AQP5, as well as for HER2 positive early breast cancer." (PMID 33947079, 2021). "Therefore, we will further discuss two aquaporins AQP3 and AQP5, representing glyceroaquaporin and orthodox aquaporin in details for their role in breast cancer." (PMID 33947079, 2021). "AGR2, APOE, AQP3, and CD99L2 may be of particular interest for the epithelial differentiating action exerted by circDOCK1-1 in TNBC-mes breast cancer cells." (PMID 34771489, 2021). "Increased levels of AQP3 channels, mediating H2O2 transport and inducing CXCL12- cell signaling and migration, could promote breast cancer metastasis." (PMID 32679804, 2020). "In agreement, transcriptomic analyses from the Human Protein Atlas database showed distinctly higher levels for AQP1 and AQP3 transcripts, with AQPs 5, 7, 9 and 11 also showing possible moderately increased levels, as compared with overall median AQP levels in breast cancer biopsies." (PMID 32679804, 2020). "The involvement of AQP3 was also demonstrated in human breast cancer cell lines expressing CXCR4 but not EGFR." (PMID 30893772, 2019). "There is an increased expression of AQP1, AQP3, and AQP5 in breast cancer." (PMID 30555637, 2018). "The expression of AQP1, AQP3, and AQP5 is up-regulated in breast cancer." (PMID 25886458, 2015). "Based on this background, we examined whether AQP3, another important member of the AQP family, could facilitate cell migration in human breast cancers." (PMID 23468877, 2013). "Based on the results, we propose that the aquaglyceroporin AQP3 is required for cytotoxic activity of 5’-DFUR and gemcitabine in the breast cancer cell line MCF7 and the colon adenocarcinoma cell line HT29, and is implicated in cell volume increase and cell cycle arrest." (PMID 23017148, 2012). "Moreover, RT-PCR analysis revealed that AQP3 and AQP7 mRNA expression was also observed in human breast cancer MCF7 cells, in addition to AQP5 expression." (PMID 22145049, 2011). "Furthermore, AQP3-mediated H2O2 transportation into cells was required to control Akt phosphorylation and consequent targeted cell migration of chemokine (C-X-C motif) ligand 2 (CXCL2)-dependent breast cancer cells in vitro." (PMID 38336645, 2024). "Thus, the combination of AQP3 and AQP9 expression may contribute to increased MMP secretion in breast cancer." (PMID 37681917, 2023). "Importantly, we validated such a negative correlation between FOXO1 and AQP3 at the protein expression level using 55 breast cancer clinical samples, with the p value from the chi-squared test being 4.63E-20 and the correlation score being -0.54." (PMID 35637961, 2022). "In breast cancer cell lines, MCF7, SUM159 and SkBr3, AQP3 was the most expressed aquaporin, and in HER2 positive cells it was upregulated together with NRF2 by H2O2 implying for then need to study effects of AQP3 overexpression in relation to the parts of antioxidative system." (PMID 33947079, 2021). "Moreover, AQP3-facilitated transport of H2O2 into cells was necessary to regulate protein kinase B (Akt) phosphorylation and subsequent directional cell migration of chemokine (C-X-C motif) ligand 2 (CXCL2)-dependent breast cancer cells in vitro." (PMID 28991174, 2017). "However, confirmation that a particular drug-modulated gene specifically contributes to drug response requires detailed analysis similar to that performed for AQP3, a gene up-regulated by the 5-FU precursor and capecitabine catabolite, 5′-DFUR, in the breast cancer cell line MCF7." (PMID 23017148, 2012). "The aim of this study is to investigate the effects of prolonged oxidative stress on Aquaporin 3 (AQP3), Aquaporin 5 (AQP5), and signaling pathways in breast cancer cell lines of different malignancies alongside a non-tumorigenic breast cell line." (PMID 38929065, 2024).
breast carcinoma (continued). "Transcriptomic analysis revealed that the three aquaglyceroporins, AQP3, AQP7 and AQP9, but not AQP10, are overexpressed in human breast cancer." (PMID 37681917, 2023). "AQP3 and AQP5 are strongly expressed in cancer tissues and AQP3-mediated H2O2 transport has been related to breast cancer cell migration, but studies with human AQP5 are lacking." (PMID 31277235, 2019). "In the present study, sorbitol treatment suppressed the migration and proliferation of breast cancer cells, where AQP5 expression was significantly decreased, but not AQP3." (PMID 22145049, 2011). "However, apart from AQP3 with a hazard ratio of 1.5, the patterns of upregulated AQP expression were not correlated with reduced survival rates in breast cancer patients, based on data available to date." (PMID 32679804, 2020).
psoriasis (42 papers, 2013 to 2026). An autoimmune condition characterized by red, well-delineated plaques with silvery scales that are usually on the extensor surfaces and scalp. "Decreased AQP3 expression is associated with skin dryness, skin aging, psoriasis, and delayed wound healing." (PMID 38611819, 2024). "Aberrant AQP3 expression is associated with atopic dermatitis and psoriasis, affecting skin hydration." (PMID 39596817, 2024). "Abnormalities of AQP3 expression are associated with the development of skin conditions such as psoriasis and atopic dermatitis." (PMID 36072192, 2022). "Down-regulation and/or mislocalization of AQP3, the most abundant and largely studied aquaglyceroporin in the skin, are associated with psoriasis and vitiligo." (PMID 33796134, 2021). "AQP3 has been found to mediate membrane hydrogen peroxide uptake, and AQP3-mediated hydrogen peroxide transport is associated with the development of psoriasis." (PMID 31382467, 2019). "Additionally, the decrease in AQP3 is caused by an excessive immunity reaction during the development of psoriasis." (PMID 38611819, 2024). "A study conducted by Hara-Chikuma et al70 on AQP3-deficient keratinocytes and AQP3-deficient mice revealed an additional role of AQP3 in the pathogenesis of psoriasis by correlating the trigger of the NF-κB pathway via extracellular HO uptake with AQP3 channel activity." (PMID 39128069, 2023). "From these facts, it is considered that the decrease in cutaneous AQP3 during type 2 diabetes may contribute to the increased risk of psoriasis." (PMID 33494453, 2021). "Moreover, cutaneous AQP3 are implicated in the development of several skin diseases, such as eczema, diabetic xeroderma, psoriasis, hyperproliferative skin disorders, or melanoma, among others, and are very important molecule that controls skin function." (PMID 34577578, 2021). "In addition, cutaneous AQP3 is known to change in various skin disorders; for example, AQP3 is decreased in psoriasis and vitiligo and during aging, causing skin dryness." (PMID 33494453, 2021). "However, elevated AQP3-associated accelerated epidermal cell proliferation may lead to diseases such as psoriasis and possibly skin tumor growth." (PMID 40927981, 2026). "Skin AQP3 is involved in the development of many skin diseases, such as eczema, diabetic xeroderma, psoriasis, and hyperplastic dermatosis; thus, it is an important molecule that controls skin function." (PMID 40247751, 2025). "There is a connection between the AQP3 amount in epidermis cells and various dermatological diseases, such as atopic dermatitis, psoriasis, vitiligo, and chronic skin pruritus." (PMID 38611819, 2024). "AQP3 peroxiporin activity is crucial for the stimulation of NF-κB signaling in keratinocytes and in the development of psoriasis." (PMID 39125952, 2024). "Consistently, a recent study reported that AQP3-mediated intracellular H2O2 production is a central event involved in NF-κB signaling activation during the development of psoriasis." (PMID 37928265, 2023). "The abnormal decrease of AQP3 expression in the epidermis is an important factor leading to skin diseases such as psoriasis and specific dermatitis." (PMID 36771204, 2023). "When Lee et al71 compared healthy skin with the skin of psoriasis patients, they found that AQP3 protein expression was reduced in perilesional and damaged skin." (PMID 39128069, 2023). "There is increasing evidence demonstrating that AQP3 in involved in inflammatory diseases including atopic dermatitis, psoriasis, allergy, and cancer progression, using AQP3−/− mice and AQP3-knockdown cells." (PMID 37006920, 2023). "A study investigating the role of AQP3 expression in the epidermis found a link between AQP3 expression and skin hydration in psoriasis." (PMID 36072192, 2022). "Abnormalities in the expression of AQP3, the most abundant skin aquaporin that facilitates skin hydration, play a role in atopic dermatitis and psoriasis." (PMID 36072192, 2022).
psoriasis (continued). "Abnormalities in aquaporin 3 (AQP3) expression and associated deficits in skin hydration appear to have a role in atopic dermatitis and psoriasis." (PMID 36072192, 2022). "In this study, 19 patients with psoriasis were compared with 10 healthy control volunteers for expression of AQP3 via immunofluorescence and by skin hydration measurements on the arm." (PMID 36072192, 2022). "Cutaneous AQP3 levels are also decreased at the onset of diabetes mellitus, vitiligo, and psoriasis, in which dry skin is observed." (PMID 34205315, 2021). "Another study reported that AQP3-null mice showed reduced psoriatic lesion development and epidermal hyperplasia, and suggested that AQP3 levels remained unchanged in psoriasis." (PMID 33796134, 2021). "Since the expressions of the pro-inflammatory cytokines (AQP3 and FLG) were suppressed by PPPs in IMQ-induced psoriasis, the underlying mechanism of their anti-psoriatic effects was further explored." (PMID 35153762, 2021). "Chinese angelica decoction has been proved to strengthen AQP3 gene and protein expressions in the guinea pig psoriasis model." (PMID 34721653, 2021). "Examples for AQP modulation of the NF-κB pathway include AQP3 dependent NF-κB activation in keratinocytes during psoriasis, in LPS-induced inflammation in macrophages during liver injury, and in B-cell activation." (PMID 33670755, 2021). "AQP3 knockout (AQP3−/−) mice showed reduced inflammation in models of contact hypersensitivity and psoriasis, and in cancer progression." (PMID 33168815, 2020). "It was reported that the AQP3 level in the skin decreases when the skin dries due to psoriasis, vitiligo, diabetes mellitus, aging, and anti-cancer drugs." (PMID 32932769, 2020). "Recently, molecular links between the circadian clock and skin hydration, and psoriasis-like inflammation have been shown to be mediated through aquaporin 3 (AQP3) in keratinocytes and IL-23R in γδ+ T cells, respectively." (PMID 30781538, 2019). "AQP3-mediated H2O2 transport is associated with necrosis factor-κB (NF-κB) signaling in keratinocytes, and in the pathogenesis of psoriasis in response to cytokine regulation." (PMID 31191567, 2019). "AQP3 expression is involved in skin diseases, including wound healing, atopic dermatitis, and psoriasis, the pathogenesis of which is attributed to AQP3’s water or glycerol transport function in epidermal keratinocytes." (PMID 28994699, 2017). "Dysregulated expression of AQP3 and Notch receptors have been reported in a number of skin diseases, including atopic dermatitis, psoriasis and skin cancer." (PMID 24260356, 2013). "Altered AQP3 expression has been linked to skin disorders, including psoriasis, nonmelanoma skin cancer, and atopic eczema." (PMID 40927981, 2026). "Moreover, IL-23-induced psoriasis in the AQP3 knockout (KO) murine model is less aggressive than in WT mice and is accompanied by impaired NF-κB activation and low intracellular H2O2 accumulation." (PMID 39125952, 2024). "Moreover, it seems that cutaneous AQP3 is increased by retinoic acid, a substance routinely used for treating psoriasis." (PMID 39063982, 2024). "Moreover, when AQP3 is overexpressed, epidermal proliferation is enhanced due to the higher AQP3-mediated glycerol permeability and can result in hyperproliferative skin disorders such as psoriasis and skin tumors." (PMID 35187089, 2022). "In recent years, it has been confirmed that AQP-3 could transport H2O2 in keratinocytes to accelerate the progression of psoriasis." (PMID 35437455, 2022). "It has been reported that cutaneous AQP3 decreases during psoriasis." (PMID 33494453, 2021). "However, although some studies have reported increased mRNA levels of AQP3 in proliferating keratinocytes in psoriasis, its expression is down-regulated with later differentiation of keratinocytes." (PMID 33796134, 2021).
psoriasis (continued). "Furthermore, AQP3 is decreased at the onset of various pathological conditions (diabetes mellitus, vitiligo, and psoriasis) in which dry skin is observed." (PMID 34577578, 2021). "Furthermore, in both AD and psoriasis, the disturbed regulation of AQP3 has been noted and is possibly related to skin dryness and increased TEWL in these diseases." (PMID 34578990, 2021). "There is increasing evidence from AQP3−/− mice and AQP3-knockdown cells for the involvement of AQP3 in various inflammatory diseases including atopic dermatitis, psoriasis, allergy, and cancer progression, in which AQP3 transport function supported cell proliferation, migration, and inflammation." (PMID 33168815, 2020). "Furthermore, skin AQP3 expression has been shown to be reduced in the presence of psoriasis, leukoplakia, diabetes mellitus, and aging, each of which cause dry skin." (PMID 32260143, 2020). "Recently, the relationships between AQP3 and skin diseases have been highlighted; it has been reported that AQP3 expression decreases during aging, psoriasis, and vitiligo but that AQP3 expression increases during atopic dermatitis, scleroderma, and skin cancer." (PMID 31382467, 2019). "However, uncontrolled AQP3 overexpression can enhance epidermal proliferation and may lead to hyperproliferative skin disorders such as psoriasis and skin tumors." (PMID 39596817, 2024). "Indeed, AQP3 plays a pivotal role in the regulation of glycerol-related metabolism in the epidermis; therefore, AQP3 inhibition has been proposed as new therapeutic strategy in many hyperproliferative skin disorders such as psoriasis, atopic dermatitis, and skin carcinogenesis." (PMID 26346093, 2015). "It has been shown that CBD also has an impact on the increase in the level of aquaporin-3 (AQP3) (at the level of mRNA and protein), which plays an important role in water retention in the skin, in psoriasis patients as well, thus improving its hydration." (PMID 36770858, 2023). "PPPs altered the mRNA expressions of the inflammatory cytokines (TNF-α, IL-6, and IL-1β) and improved the expressions of AQP3 and FLG in psoriasis-like mouse skin." (PMID 35153762, 2021). "Decreased levels of AQP3 and FLG are commonly seen in skin barrier disruption, which appears to be a key player in epidermal biology in psoriasis." (PMID 35153762, 2021). "Therefore, it is still controversial whether AQP3 is up- or down-regulated in psoriasis." (PMID 33796134, 2021). "The induction of psoriasis by cytokines, NF-κB activation, and intracellular H2O2 accumulation are concomitantly reduced in AQP3-knockout mice." (PMID 31191567, 2019). "Reduced levels of AQP-3 result in impairments in skin hydration, elasticity, glycerol content in skin and is also found in psoriasis patients; however, there is no report regarding whether exogenous aging PMs factors would cause AQP-3 expression to affect skin moisture." (PMID 31398912, 2019). "Previously, it was proven that the differences in TEWL and SCH values between lesional and non-lesional skin in psoriasis are due to decreased levels of aquaporin-3 (AQP3) expression." (PMID 39063982, 2024). "In addition, disorders of ceramide subtypes and skin lesions result in cuticular extracellular matrix dysfunction, low expression of aquaporin-3 (AQP3), and fibroblasts in psoriasis, all contribute to the dysfunctional physical barrier." (PMID 36314037, 2022). "AQP3 KO mice with IL-23-induced psoriasis showed that AQP3, a water/glycerol/hydrogen peroxide (H2O2) channel protein, is required for nuclear factor-κB (NF-κB) activation and signaling in keratinocytes and in the pathogenesis of psoriasis." (PMID 33673336, 2021). "Overall, these results indicated that PPPs ameliorated the symptoms of psoriasis through inhibition of the inflammatory cytokines by suppressing the NF-κB and STAT3 signaling pathways and improved skin barrier protection via enhancing AQP3 and FLG." (PMID 35153762, 2021).
psoriasis (continued). "T cell migration toward chemokines resulted in being dependent on AQP3-mediated hydrogen peroxide uptake and AQP3 was shown to mediate H2O2 transport correlated to inflammation in keratinocytes and the development of psoriasis." (PMID 30893772, 2019). "Notably, the PLD2/AQP3 signaling module was observed to be abnormal in psoriasis and non-melanoma skin cancers, suggesting a possible involvement of dysregulation of this module in such hyperproliferative skin diseases." (PMID 32528559, 2017). "In addition, PPPs significantly suppressed the NF-κB and STAT3 pathways and accentuated the expressions of AQP3 and FLG when compared to mice with IMQ-elicited psoriasis without treatment." (PMID 35153762, 2021).